GALR3 (galanin receptor 3)
Description:
Receptor for the hormone galanin. Receptor for the hormone spexin-1.
Tractability: Small molecule: a high-quality ligand is known; it belongs to a druggable protein family. Antibody: its Gene Ontology location is reachable by antibodies, with high confidence; UniProt places it where antibodies can reach, with medium confidence; UniProt predicts a signal peptide or a membrane-spanning region. PROTAC: a small molecule that binds it is known.
Target class: Membrane receptor; Peptide receptor (family A GPCR); Family A G protein-coupled receptor; Galanin receptor; Short peptide receptor (family A GPCR)
Gene: Protein-coding gene on chromosome 22 (37,822,198 to 37,825,485, forward strand). Ensembl gene ENSG00000128310.
Subcellular location: Cell membrane
Pathways (Reactome):
Signal Transduction: G alpha (i) signalling events; Peptide ligand-binding receptors
Gene Ontology:
Molecular function: galanin receptor activity; peptide hormone binding; protein binding; G protein-coupled receptor activity
Biological process: G protein-coupled receptor signaling pathway, coupled to cyclic nucleotide second messenger; galanin-activated signaling pathway; positive regulation of transcription by RNA polymerase II; chemical synaptic transmission; feeding behavior; learning or memory; neuropeptide signaling pathway; G protein-coupled receptor signaling pathway
Cellular component: cilium; membrane; plasma membrane; 9+0 non-motile cilium; non-motile cilium; synapse
Genetic constraint (gnomAD): Loss-of-function variants: 6 observed, 5.61 expected, observed/expected ratio (o/e) 1.07, 90% interval 0.57 to 1.82. That is too few expected variants to judge how well the gene tolerates losing a copy. Missense variants: 566 observed, 369.48 expected, observed/expected ratio (o/e) 1.53, 90% interval 1.43 to 1.64. Synonymous variants: 305 observed, 187.97 expected, observed/expected ratio (o/e) 1.62, 90% interval 1.48 to 1.78.
Homologues: Orthologues: chimpanzee GALR3 (99% identical), macaque GALR3 (97% identical), pig GALR3 (93% identical), rabbit GALR3 (93% identical), dog GALR3 (92% identical), rat Galr3 (91% identical), mouse Galr3 (90% identical), zebrafish galr2b (46% identical). Paralogues in human: GALR1 (32% identical), NPFFR1 (27% identical), CCKBR (24% identical), NPFFR2 (23% identical), AVPR1B (22% identical), HCRTR2 (22% identical), CCKAR (22% identical), HCRTR1 (21% identical), QRFPR (21% identical), OXTR (21% identical), AVPR2 (20% identical), AVPR1A (18% identical), and 4 more.
Diseases named in the same sentence as GALR3 in open-access papers:
GALR3 is named in the same sentence as 38 diseases in open-access papers, as found by Europe PMC text mining. Sharing a sentence is not in itself a finding about the gene and the disease. The quoted sentences say what the papers report.
Anxiety (10 papers, 2006 to 2025). Intense feelings of nervousness, tension, or panic often arise in response to interpersonal stresses. "First, SPX1 has the capacity to bind Galr2 and Galr3, which are implicated in anxiety and depression-like behaviors in mice." (PMID 31474838, 2019). "The three galanin receptor subtypes, GALR1, GALR2, and GALR3, are widely distributed in mood-related brain areas such as hypothalamus, central amygdaloid nucleus, and thalamus and may mediate anxiety-associated behavior." (PMID 16623937, 2006). "While little interest has been paid to GalR3 in relation to mood, possibly due to its low expression in the rat and mouse brain, a GalR3 knockout mouse exhibits an anxiety-like phenotype." (PMID 30627087, 2018). "Notably, male Galr3-KO mice exhibited an anxiety-like phenotype and reduced social affiliation." (PMID 39968178, 2025). "For example, galanin receptor 3 (GALR3) was expressed more in males than females, and galanin, its ligand, has been implicated in several clinical conditions that are known to affect one sex more than another, including depression and anxiety and human alcoholism." (PMID 23613935, 2013). "GalR1 and GalR2 are expressed throughout the brain,while GalR3 is confined to the hypothalamus It has been postulated that the dysregulation of the normal interaction between NE and Gal in the amygdala may contribute to stress-related disorders, such as depression, anxiety and PTSD." (PMID 27907151, 2016).
depression (9 papers, 2013 to 2026). "The higher relevance of the GalR2, GalR3 and GalR1 gene polymorphisms in stress-induced depression and the galanin system-independent effects of the currently used antidepressants suggest that novel antidepressants acting on GalR1-3 could be developed." (PMID 30627087, 2018). "Activation of GALR1 and GALR3 induces depression-like behaviors, whereas activation of GALR2 inhibits depressive-like behaviors." (PMID 40048451, 2025). "On the basis of these studies, it is hypothesized that galanin may, via inhibitory GalR3 autoreceptors, act as a ‘brake’ to prevent overexcitation of LC neurons, representing a resilience mechanism to protect against depression." (PMID 30627087, 2018). "Depression-like behaviors seem to be induced by the activation of GALR1 and attenuated depression-like behaviors derived by the activation of GALR3." (PMID 23986909, 2013).
psoriasis (4 papers, 2019 to 2021). An autoimmune condition characterized by red, well-delineated plaques with silvery scales that are usually on the extensor surfaces and scalp. "Mice without the GALR3 gene had reduced psoriasis symptoms as a result of delayed angiogenesis, reduced neutrophil infiltration, and lower levels of cytokines." (PMID 31910243, 2020).
colorectal cancer (3 papers, 2022 to 2023). A primary or metastatic malignant neoplasm that affects the colon or rectum. "Colorectal cancer patients (n = 8) with shorter survival and poorer prognosis exerted a lower immunoreactivity of GalR3 compared to higher expression of this protein in non-cancerous epithelial cells (Figure 6A2,B2)." (PMID 35409094, 2022).
glioblastoma multiforme (3 papers, 2017 to 2022). "Sequences involved in sorting are often present in the 3′-UTR of the mRNAs: one example is mRNA encoding galanin receptor 3 (GalR3), found in human primary glioblastoma multiforme cells and enriched in the exosomes produced by these cells." (PMID 28937658, 2017).
Anorexia (1 paper, 2022). Lack of desire to eat (loss of appetite). "Thus, we sought to identify whether SPX action on leptin-induced anorexia is mediated via GALR2 and/or GALR3." (PMID 35204737, 2022).
dermatitis (1 paper, 2016). An inflammatory process affecting the skin. "Studies on the involvement of GalR3 in inflammatory processes are occasional and only its role in the regulation of microvasculature and oedema formation in dermatitis has been described." (PMID 27175780, 2016).
dyspepsia (1 paper, 2020). An uncomfortable, often painful feeling in the stomach, resulting from impaired digestion. "Interestingly, GalR3 had no functional involvement in the regulation of tension and mucosal gastric vagal receptor mechanosensitivity, thus, it is probably involved in other kinds of afferent sensation (as previously suggested dyspepsia)." (PMID 33227035, 2020).
endometrial cancer (1 paper, 2025). Primary or metastatic malignant neoplasm involving the endometrium (mucous membrane that lines the endometrial cavity). "GalR3, a cancer-dependent gene, plays a role in cancer progression, albeit its specific role in endometrial cancer unreported." (PMID 39926275, 2025).
head and neck squamous cell carcinoma (1 paper, 2023). A squamous cell carcinoma that arises from any of the following anatomic sites: lip and oral cavity, nasal cavity, paranasal sinuses, pharynx, larynx, and salivary glands. "Galanin (GAL) stimulates a variety of signal transduction and integration pathways by activating its receptors GALR1, GALR2, and GALR3,14, 15 and thus far, GALRs have been found to be the most effective markers for predicting the prognosis of head and neck squamous cell carcinoma (HNSCC) patients." (PMID 36039037, 2023).
Hepatic steatosis (1 paper, 2023). Steatosis is a term used to denote lipid accumulation within hepatocytes. "Spexin, a neuropeptide in the galanin family, has been shown to activate GALR2/GALR3 (but not GALR1) and mitigate diet-induced hepatic steatosis in vivo and in vitro by activating GALR2." (PMID 37180164, 2023).
inflammatory bowel disease (1 paper, 2026). A spectrum of small and large bowel inflammatory diseases of unknown etiology. "Galanin mitigated inflammatory bowel disease (IBD) in rats, but the absence of galR3 led to increased local and systemic levels of inflammatory cytokines and chemokines." (PMID 41546485, 2026).
lymph node metastasis (1 paper, 2022). "Univariate Cox proportional hazards regression revealed that lower relative GalR3 protein immunoexpression, as well as the presence of distant metastases and lymph node metastasis, were associated with the overall survival of the patients." (PMID 35409094, 2022).
Obesity (1 paper, 2024). Accumulation of substantial excess body fat. "It is known that GALR2 increases during obesity, but different results have been found for GALR3." (PMID 38339044, 2024).
tumor (9 papers, 2002 to 2025). "The distribution of GALR3 was associated with tumour size—T, invasion of regional lymph nodes—N, and distant metastases—M (TNM staging system), as well as with the overall survival of CRC patients." (PMID 36551197, 2022). "The average immunoreactivity of GALR1 and GALR3 in muscularis externa plexuses close to the CRC tissue was slightly reduced as compared to the plexuses distant from the tumour, while GALR2 immunoreactivity reminded unchanged (p = 0.0351, p = 0.0204 and p = 0.1109, respectively)." (PMID 36551197, 2022). "Similarly, the GalR3 immunoreactivity of tumor cells was significantly higher than that of epithelial cells of the unchanged mucosa (63.64 ± 3.28 and 48.36 ± 4.32, respectively, p = 0.0042)." (PMID 35409094, 2022). "Moreover, the lower relative GalR3 distribution is correlated with the higher cancer clinical stage (size of the primary tumor—T, spread to regional lymph nodes—N)." (PMID 35409094, 2022). "It is thus speculated that the upregulation of GALR3 in DLBCL may indirectly affect immune cell functions and immune factor secretion through the nervous system, alter the tumor microenvironment, and influence the disease progression of DLBCL." (PMID 41142795, 2025). "The immunohistochemical and immunofluorescent methods showed only slightly decreased immunoexpression of GALR1 and GALR3 in myenteric plexuses close to cancer but did not reveal any correlation in the immunoexpression of all three GAL receptors in myenteric plexuses and tumour progression." (PMID 36551197, 2022).
cancer (3 papers, 2022 to 2025). A tumor composed of atypical neoplastic, often pleomorphic cells that invade other tissues. "We found that GALR1, GALR2 and GALR3 relative immunoreactivity (comparing myenteric plexuses close to CRC cells vs. plexuses distant from cancer invasion) did not correlate with the overall survival of CRC patients." (PMID 36551197, 2022). "We found that GALR1, but not GALR2 and GALR3, relative immunoreactivity (comparing submucosal plexuses close to CRC cells vs. plexuses distant from cancer invasion) correlate with the overall survival of CRC patients (p = 0.0115 and HR = 4.97) and clinical-pathological data of CRC patients." (PMID 36551197, 2022).
heart diseases (1 paper, 2025). "The data on the role of GalR1 and GalR3 in heart diseases are controversial or missing." (PMID 39968178, 2025).
infection (1 paper, 2020). The state of being infected such as from the introduction of a foreign agent such as serum, vaccine, antigenic substance or organism. "Surprisingly, despite the widespread infection with the virus, changes in the transcriptome remained limited to only a few genes: GALR3, EGR1, E2F2, RNY4, DBX2 were found upregulated, and ITM2C was downregulated." (PMID 33490061, 2020).
GALR3 also shares sentences with these, for which no sentence is quoted: glioma (3 papers); colitis (2); pituitary adenoma (2); alcoholism (1); anaplastic astrocytoma (1); astrocytic tumor (1); cholestasis (1); Crohn disease (1); diffuse astrocytoma (1); ganglioglioma (1); giant cell glioblastoma (1); gliosarcoma (1); metabolic disease (1); mood disorder (1); oligodendroglioma (1); pilocytic astrocytoma (1); pituitary tumor (1); prostate carcinoma (1); stress-related disorder (1); ulcerative colitis (1).